IL6R (interleukin 6 receptor)
Diseases named in the same sentence as IL6R in open-access papers (continued):
Sharing a sentence is not in itself a finding about the gene and the disease.
autoimmune disease (continued). "Vobarilizumab, binding interleukin‐6 receptor (IL‐6R), was developed by Ablynx for the treatment of autoimmune diseases and confirmed its low immunogenicity through clinical trials." (PMID 36153698, 2022). "Other IL-6/IL-6R blockades that are FDA-approved or undergoing RCT for autoimmune diseases include clazakizumab, siltuximab, sarilumab, olokizumab, sirukumab, and tofacitnib." (PMID 34441950, 2021). "However, in IL-6 cluster signaling, the IL-6/IL-6Rα complex forms internally in dendritic cells (DCs) and interacts with gp130 expressed on antigen-specific T cells, a pathway which may be relevant to multiple T lymphocyte-associated autoimmune diseases." (PMID 33816637, 2021). "Tocilizumab (TCZ) is a humanised anti‐interleukin (IL)‐6 receptor (IL‐6R) monoclonal antibody that is a promising agent to treat various autoimmune diseases." (PMID 33163184, 2020). "ALX-0061 targets IL-6R and is currently in clinical development for the treatment of autoimmune diseases, such as RA." (PMID 25994180, 2015). "Also, in contrast to patients with autoimmune disorders receiving repeated dosages of anti-IL-6R therapy, MI patients received one dosage." (PMID 41543641, 2026). "In addition to its function as the TNFα convertase, ADAM17 also cleaves a myriad of other membrane tethered proteins to shed them from the cell membranes, including the interleukin 6 receptor (IL-6R), a key player in autoimmune disease." (PMID 40512800, 2025). "In addition, NEF binders can be further characterized for their IL-6R-blocking function in autoimmune diseases such as IgA nephropathy." (PMID 38715108, 2024). "Several autoimmune disorders have been linked to polymorphisms in IL10 and IL6R genes." (PMID 38822340, 2024). "Activation of classical (IL-6/IL-6R) or trans signaling (IL-6/sIL6R) occurs via gp130 and contributes to the sequestration of excess IL-6; blocking trans-signaling is effective in preclinical chronic and autoimmune diseases." (PMID 39553645, 2024). "IL6R gene may be involved in the development and treatment of autoimmune diseases including uveitis." (PMID 38822340, 2024). "IL-6 also promotes Th17 differentiation and inhibits Treg differentiation, suggesting targeting IL-6/IL-6R may have clinical applications in treating autoimmune disease and organ rejection." (PMID 34441950, 2021). "Interestingly, activated CD4+ T cells have been shown to increase levels of soluble IL-6R via IL-6R shedding; this mechanism is thought to have a role in the development of autoimmune diseases, which are often mediated by autoreactive T cells." (PMID 31276585, 2019). "Mimotopes identified for IL-6R may represent a novel alternative for treating RA or other autoimmune diseases." (PMID 26033236, 2015). "Indeed, the blockade of the IL-6/IL-6R signaling axis using tocilizumab, a humanized anti-IL-6R antibody, has become a therapeutic option to treat autoimmune diseases." (PMID 25884400, 2015). "Furthermore, blocking of IL6R has been shown to ameliorate autoimmune disease in a number of model systems, suggesting that macrophage expansion may be a key driver of early disease." (PMID 30453645, 2018). "Tocilizumab (Actemra, Chugai Pharmaceutical Co., Ltd., Tokyo, Japan), a humanized anti-human IL-6 receptor (IL-6R) monoclonal antibody that inhibits IL-6 binding to IL-6R might inhibit the biologic function of IL-6, which plays a pivotal role in the pathogenesis of autoimmune diseases." (PMID 23424706, 2012). "IL1RL2, IL6R, ERBB3, ICAM1, IL1R1, and GALK1 were also enriched in categories like immune system disease, autoimmune disease, skin disease, and disease of anatomical entity." (PMID 38773393, 2024). "The action of IL-6 can be blocked by anti-IL-6R antibody, e.g., tocilizumab or ALX-0061, which effectiveness was proven for autoimmune disease treatment." (PMID 40589521, 2023).
autoimmune disease (continued). "Thus, our findings highlight the possible biological relevant ligand for IL-6R, which is of great importance for filling out the current knowledge of the IL-6/IL-6R/gp130 buffer system, and provide a potential inhibitor for clinical application in autoimmune diseases." (PMID 38015631, 2023). "In addition to these cytokines, the results of the qPCR array also showed the expression levels of IL-6R, CCL17, and ACKR1, which are related to inflammatory responses or autoimmune diseases." (PMID 39771147, 2024). "In addition, recent studies have reported the potential roles of IL-6R, IL-13, and CCL11/Eotaxin in autoimmune diseases such as primary Sjögren’s syndrome through T and B helper cells." (PMID 36187125, 2022). "In the case of patients with autoimmune diseases, treatments are based on drugs such as anti-TNF agents and interleukin-6 receptor blockers, thus favoring the onset of infections by blocking the signal transduction from the cell surface receptors to the nucleus." (PMID 35054223, 2021). "We chose IL2RA because of its known association with a broad spectrum of autoimmune diseases, including JIA, and IL6R because this locus does not appear on GWAS for any other autoimmune disease and, thus, its effects appear to be specific for JIA." (PMID 32730263, 2020). "The differences in the metabolic responses to anti-IL6R response between patients with autoimmune diseases and NSTEMI/STEMI patients are not clear, but could include more use of statins in the MI patients that reduce LDL levels, but may increase Lp(a) levels." (PMID 41543641, 2026).
coronary heart disease (57 papers, 2012 to 2026). "rs2228145 (also referred to as rs8192284) is within the IL6R gene and has been linked to sIL-6r levels and coronary heart disease risk." (PMID 40373041, 2025). "Genetically predicted IL-6R inhibitors were associated with a protective effect against coronary heart disease and myocardial infarction." (PMID 39897309, 2025). "This approach has been used in MR analyses to demonstrate that genetically proxied IL6R inhibition is significantly associated with reduced risk of coronary artery disease and ischemic stroke." (PMID 37914784, 2023). "This was supported by two large meta-analyses that confirmed the crucial role played by a variant allele of the IL6R gene encoding the IL-6 receptor in the generation of inflammation and the associated risk of coronary heart disease." (PMID 37762312, 2023). "Due to the different effects of the IL6R gene on diabetes and coronary heart disease, further research is still needed to demonstrate the association between IL6R variants and diabetic macrovascular complications." (PMID 35330392, 2022). "Genetic studies have indicated that the presence of the T allele of rs4845625 in the intron of the IL6R gene was associated with an increased risk of cardiovascular disease such as coronary artery disease and atrial fibrillation." (PMID 36060677, 2022). "Here, we demonstrate this novel approach, TSCMR, through simulation experiments and an applied example considering the effect of interleukin 6 receptor signaling on coronary artery disease risk." (PMID 36140709, 2022). "Lastly, the genetic variation in IL6R was associated with atherosclerotic manifestations, such as coronary artery disease, peripheral artery disease, and aortic aneurysms." (PMID 36555579, 2022). "For IL6R rs4845625, participants with the CT and TT genotypes had a significantly lower risk of diabetic ischemic heart disease than those with the CC genotype (OR = 0.692, p = 0.045; OR = 0.503, p = 0.003, respectively)." (PMID 35330392, 2022). "Here, through simulation experiments and an applied example considering the effect of interleukin 6 receptor signaling on coronary artery disease risk, we present an alternative method for attenuating bias that does not suffer from this problem." (PMID 36140709, 2022). "A previous meta-analysis demonstrated that the C allele in rs7529229 IL6R was associated with a lower risk of coronary heart disease." (PMID 35330392, 2022). "While the comparison was done with Eastern Europeans, we identified significant signals in PKD2L1 and IL6R which are genes associated with taste and coronary artery disease, respectively." (PMID 30510563, 2018). "IL6R encodes the receptor for the pro-inflammatory cytokine interleukin-6 and circulating levels of a soluble form of IL6R have been associated with coronary artery disease." (PMID 25835000, 2015). "Meta-analysis of 34 studies including 25 458 coronary heart disease cases and 100 740 controls suggested the same IL6R rs7529229 variant was associated with reduced odds of coronary heart disease events." (PMID 22421340, 2012). "On the basis of genetic evidence in human beings, IL6R signalling seems to have a causal role in development of coronary heart disease." (PMID 22421340, 2012). "Our study provides strong evidence in human beings for a causal role of a specific inflammatory mechanism (ie, IL6R signalling) in coronary heart disease." (PMID 22421340, 2012). "We then undertook a large-scale collaborative genetic association analysis of IL6R variants with coronary heart disease events and stroke and examined safety endpoints, including infections and common cancers." (PMID 22421340, 2012). "Applying the mendelian randomisation principle, we used single nucleotide polymorphisms (SNPs) in the gene IL6R to evaluate the likely efficacy and safety of IL6R inhibition for primary prevention of coronary heart disease." (PMID 22421340, 2012).
coronary heart disease (continued). "In 25 458 coronary heart disease cases and 100 740 controls, the IL6R rs7529229 SNP was associated with a decreased odds of coronary heart disease events (per allele odds ratio 0·95, 95% CI 0·93–0·97, p=1·53×10−5)." (PMID 22421340, 2012). "Notably, the strong associations observed between the IL6R variant and cardiovascular phenotypes, e.g. coronary heart disease, aortic aneurysms, peripheral arterial disease observed in prior studies was confirmed in EUR but not AFR6,17,44." (PMID 38580710, 2024). "This stratification approach has been used to show that the effect of smoking on risk of bladder cancer is greater for those with low bodyweight, and that the effect of interleukin-6 receptor inhibition on coronary heart disease risk is greater for those with high levels of C-reactive protein." (PMID 36736292, 2023). "Mendelian randomization analysis illustrated that IL6R signaling might have a causal role in the development of coronary heart disease." (PMID 35330392, 2022). "For example, an association between a genetic polymorphism of interleukin-6 receptor (IL-6R) and risk of coronary heart disease has led to RCTs of tocilizumab, an IL-6R inhibitor (also an effective biological disease-modifying anti-rheumatic drug DMARD), in myocardial infarction." (PMID 32571398, 2020). "Recent genetic analysis using the Mendelian Randomization principle suggested that IL-6R signaling indeed plays a causal role in the development of coronary artery disease, suggesting IL-6R inhibition could be a potential new target in coronary artery disease." (PMID 27936014, 2016). "Recent data suggest a causal role of the IL-6 receptor (IL-6R) in coronary heart disease." (PMID 27936014, 2016). "We also examined the association of IL6R variants with coronary heart disease." (PMID 22421340, 2012). "We applied mendelian randomisation to examine whether IL6R modulation is likely to reduce risk of coronary heart disease in the general population." (PMID 22421340, 2012). "A previous MR analysis suggested that reduced IL-6 signalling (modelled using rs2228145 alone) could reduce inflammation and risk of coronary heart disease, leading to clinical trials of monoclonal antibodies targeting either IL6R or IL-6 for coronary disease prevention." (PMID 36716318, 2023). "Indeed, genome-wide association studies suggest that IL-6R signaling is likely to have great effects on the vascular risk and blocking IL-6R may be a therapeutic approach to prevent coronary heart disease." (PMID 29694426, 2018). "Variants at the interleukin 6 receptor (IL6R) gene regulate inflammation and are associated with risk of coronary heart disease (CHD)." (PMID 25781951, 2015). "High circulating interleukin-6 concentration is associated with increased risk of coronary heart disease in observational studies and preliminary evidence suggests a variant in the gene for its receptor (IL6R) might be associated with reduced risk of coronary heart disease." (PMID 22421340, 2012). "Although the IL6R rs7529229 variant was associated with reduced circulating C-reactive protein and fibrinogen concentrations, this study should not be interpreted as a mendelian randomisation analysis investigating causality of C-reactive protein or fibrinogen in coronary heart disease." (PMID 22421340, 2012). "The most co-cited article was an article entitled the interleukin-6 receptor as a target for prevention of coronary-heart-disease: a Mendelian randomization analysis, written by Daniel I Swerdlow." (PMID 38579070, 2024). "The neutral result from the IL1β analysis in the present study is notable given that IL1β is upstream of IL6R, and previously reported evidence supports a protective effect of canakinumab for patients with coronary disease." (PMID 37914784, 2023). "Compared with coronary artery disease, there is less evidence supporting IL6R signaling pathway contributing to carotid atherosclerotic diseases." (PMID 36060677, 2022).
coronary heart disease (continued). "A meta-analysis showed that the risk of coronary heart disease is reduced by 3.4% for every copy of IL-6R with Asp358Ala inherited, suggesting a relationship between IL-6R and coronary heart disease." (PMID 30423923, 2018). "If variants in the IL6R gene region were assumed to be instrumental variables for CRP, then the false conclusion would be reached that CRP was causal for coronary heart disease risk." (PMID 26291580, 2016). "Examples of genetic variants which have been used in this way for coronary heart disease include variants in the CRP gene for the causal effect of C-reactive protein, and variants in the IL6R gene for the causal effect of interleukin-6 receptor." (PMID 24062299, 2013). "Comparison of the genetic findings with data from randomised trials of tocilizumab supports further evaluation of IL6R inhibition as a therapeutic strategy for prevention of coronary heart disease." (PMID 22421340, 2012). "Risk of incident infection would be an important safety consideration in any trial of IL6R inhibition for prevention of coronary heart disease." (PMID 22421340, 2012). "However, whether IL6R blockade also reduces risk of coronary heart disease is unknown." (PMID 22421340, 2012). "Similar to IL6R, we found that genetically downregulated IL-6 signaling via IL6 perturbation is associated with lower lifetime risks of coronary artery disease, peripheral artery disease and ischemic atherosclerotic stroke in individuals of European and East Asian ancestry." (PMID 40858837, 2025). "As a simple example, genetic predictors of C-reactive protein concentrations in the IL6R region are associated with coronary artery disease risk, but those in the CRP region are not." (PMID 36736292, 2023). "Finally, we established a causal patho-mechanistic network of GE and PE of IL6R, PCSK9, TFPI, and AXL and coronary artery disease providing possible new therapy targets." (PMID 35604899, 2022). "For example, IL6R was previously proposed as a target for preventing coronary heart disease." (PMID 28240269, 2017). "Furthermore, two large mendelian randomized studies showed that polymorphisms of the IL-6R are associated with reduced CRP levels and the risk of coronary artery diseases." (PMID 24244750, 2013). "IL6R blockade could provide a novel therapeutic approach to prevention of coronary heart disease that warrants testing in suitably powered randomised trials." (PMID 22421340, 2012). "This mendelian randomisation analysis suggests that IL6R signalling is involved in coronary heart disease and that the IL6R could be a valuable target for the prevention or treatment of coronary heart disease." (PMID 22421340, 2012). "However, these ongoing trials will not answer the question of whether IL6R blockade will modify risk of coronary heart disease in the general population." (PMID 22421340, 2012). "We searched Medline via PubMed for “tocilizumab AND (“coronary heart disease” OR “myocardial infarction”), for “interleukin-6 receptor AND (“coronary heart disease” OR “myocardial infarction”), and for “IL6R” AND (“coronary heart disease” OR “myocardial infarction”) up to Jan 8, 2012." (PMID 22421340, 2012).